AFP (alpha fetoprotein)
Diseases named in the same sentence as AFP in open-access papers (continued):
Sharing a sentence is not in itself a finding about the gene and the disease.
Cirrhosis (continued). "Patients with HCC, larger tumor sizes, liver cancer with hepatic cirrhosis, portal vein thrombosis, metastasis, high Child–Pugh score, high Barcelona-Clínic Liver Cancer (BCLC) stage, and advanced clinical stage had significantly higher serum AFP levels." (PMID 35461226, 2022). "In the validation cohort, the patients with or without cirrhosis had a significant difference between AFP ratio high and AFP ratio low (p = 0.009)." (PMID 35059044, 2022). "Through multivariate analysis, preoperative AFP level>100ng/ml (p=0.004), absence of cirrhosis (p<0.001), satellite lesions (p=0.004), maximal diameter>5cm (p=0.010) and presence of PVTT (p<0.001) were identified as independent risk factors for RFS." (PMID 36203429, 2022). "In addition, most studies focus selectively on the relationship between AFP levels and HCC in cirrhosis." (PMID 36233670, 2022). "Current recommendations for screening consist of semiannual abdominal ultrasound with or without serum alpha fetoprotein (AFP) in patients with cirrhosis and in demographic subgroups with chronic hepatitis B infection." (PMID 36479252, 2022). "The score of 0 was assigned to age ≤60 years, female, Child‐Pugh class A, no cirrhosis, serum AFP ≤400 μg/L, no vascular invasion, tumor stage I–II, and tumor grade 1–2." (PMID 35141283, 2022). "In particular, the diagnostic performances of the ASAP and GALAD scores in subgroups of HCV-HCC and HCC-cirrhosis among AFP-negative patients was evaluated." (PMID 36263214, 2022). "On the other hand, the rest of the DAAs-treated patients (both compensated cirrhosis and F3 hepatitis) presented with significantly smaller tumours (mean HCC size being 3.5 and 3 cm, respectively) and had lower AFP levels, mostly between 100 and 300 ng/ml-in accordance to their dimensions." (PMID 35497085, 2022). "According to the differential expression of serum lnc85, AFP-negative HCC patients can be distinguished from cirrhosis and healthy control group." (PMID 35126514, 2022). "Additionally, increased AFP values prevailed in patients with cirrhosis and HCC, compared to the group with cirrhosis, corroborating the literature, also presenting itself as an independent factor for the disease." (PMID 35919232, 2022). "Wide margins have been suggested for small (<5 cm) HCCs, non-anatomic resections, and HCCs with microvascular invasion, without cirrhosis, or with high alpha-fetoprotein (AFP) levels." (PMID 35910466, 2022). "Tumor size (P = 0.002), cirrhosis (P = 0.041), BCLC stage (P = 0.050, 0.004 and < 0.001 for A stage, B stage and C stage, respectively), serum AFP (P = 0.049) and TNM stage (P = 0.005 and < 0.001 for II stage and III or IV stage, respectively) were statistically significant for OS in HCC patients." (PMID 35193513, 2022). "In the univariable and multivariable analysis, it was shown that several baseline factors were associated with tumor recurrence and overall survival after RFA: serum PLT, ALT, HBV DNA, AFP, ALBI grade, tumor size, and the presence of cirrhosis in the full cohort." (PMID 35458386, 2022). "This is a retrospective cohort study on patients living with HIV-1 infection (PLWH) followed at the Division of Infectious Diseases of the San Raffaele Hospital, with cirrhosis and HCC diagnosed between 1999 and 2018 and with an available AFP value at HCC diagnosis." (PMID 35186078, 2022). "Secondly, the study population included patients in different phases of the disease evolution (cirrhosis, early-stage HCC, and metastatic HCC) and the values of AFP, ESR, and CRP may greatly differ at these different stages of the disease." (PMID 35200757, 2022). "Not all patients in the study group had a recorded AFP level, which further decreased the number of patients, thus precluding us from dividing them according to the etiology of cirrhosis." (PMID 35626300, 2022).
Cirrhosis (continued). "The serum AFP levels of these HCC patients were not significantly different from those of 30 CHB patients without HCC (including 19 HBV-related cirrhosis patients and 11 CHB patients without cirrhosis) (p = 0.053)." (PMID 36421714, 2022). "In subgroup analysis, 68Ga-FAPI-04 PET/CT was more sensitive than 18F-FDG PET/CT in the detection of intrahepatic lesions in patients with cirrhosis, low α-fetoprotein (AFP), multiple tumours, and non-serious MVI (M0 and M1) (all P < 0.05)." (PMID 34249748, 2021). "Among the traditional HCC biomarkers, protein induced by vitamin K absence or antagonist II (PIVKA-II), alone or in combination with alpha-fetoprotein (AFP), showed promising results for the early detection, and even for the prediction, of HCC in patients with cirrhosis of viral etiology." (PMID 34064999, 2021). "Additionally, the N-glycopeptide Asn207 + 5-6-0-1 better differentiated between cirrhosis and early HCC than AFP." (PMID 34436504, 2021). "Conversely, patients who were not diagnosed with HCC but displayed cirrhosis, cholangiocarcinoma, or other tumors were shown to contain elevated AFP." (PMID 34771525, 2021). "Interestingly, the FokI TT genotype was also associated with HCC clinicopathology characterized by increased serum alpha-fetoprotein (AFP), advanced tumor stage, cirrhosis, and lymph node metastasis." (PMID 34113565, 2021). "Consistently, AFP showed an AUC value of 0.710, 95% CI 0.634–0.778 (p < 0.001) for the discrimination between cirrhosis and HCC, while serum ERBB3 was not able to discriminate between the two groups of patients (AUC = 0.500, 95% CI 0.421–0.579, p = 0.994)." (PMID 33799723, 2021). "WGCNA was performed on GSE14520 dataset to create gene modules associated with clinical traits including survival time, survival state, gender, age, HBV infection, ALT level, main tumor size, multinodular, cirrhosis, TNM staging, BCLC staging, CLIP staging and AFP level." (PMID 33753986, 2021). "Interestingly, the non-fucosylated N-glycopeptide Asn207 + 5-6-0-1, better differentiated between the cirrhosis and early HCC group samples than AFP." (PMID 34436504, 2021). "Moreover, the univariate Cox regression analysis indicated no considerable correlation between median PFS or median OS with age, Child–Pugh, cirrhosis, HBV infection, and AFP level." (PMID 34458205, 2021). "Clinical T stage, age, presence of cirrhosis, AFP levels, and haemoglobin levels were included in the nomogram as independent predictive factors." (PMID 34126955, 2021). "Alpha-fetoprotein (AFP) and cirrhosis history were also examined." (PMID 33916685, 2021). "The clinical information of 242 HCC patients who meet the criteria in the GSE14520 dataset includes age, ALT (>/<=50 U/L), main tumour size (>/<=5 cm), multinodular cirrhosis, TNM staging, BCLC staging, CLIP staging and AFP (>/<=300 ng/ml) were included in the analysis." (PMID 33962640, 2021). "Pre-operative AVT was a protective factor of RFS for patients with high or low load of HBV-DNA load, high or low level of AFP, positive HBeAg, tumor size (>5 cm), cirrhosis, MVI, and for those without EGV (all P<0.05)." (PMID 33391413, 2021). "In addition, a second model has been described, the LCR2 model, which is used to follow individuals identified by LCR1 and patients with cirrhosis; LCR2 includes the same variables combined with AFP." (PMID 33918270, 2021). "Additionally, in randomized trials for hepatitis C antiviral long-term treatment against cirrhosis, DCP has shown sensitivity and specificity comparable to those of AFP." (PMID 33562077, 2021). "Sex; race; marital status; year of diagnosis; pathological grade; T, N, and M stages; tumour size; AFP level; radiation; chemotherapy; surgery; and no cirrhosis/cirrhosis were identified as significant predictors for survival." (PMID 32913474, 2020).
Cirrhosis (continued). "The average AFP serum levels in patients with compensated cirrhosis without HCC were 9.4 ng/ml (range 0.5 ÷ 406 ng/ml); 30.1% of patients had significantly increased levels of AFP (>15 ng/ml)." (PMID 32341704, 2020). "However, the AFP levels of 40% of HCC patients are normal, and elevated levels of AFP are also reported in patients with viral hepatitis, cirrhosis, pregnancy, and the presence of other tumors, such as germ cell tumors and gastric cancer." (PMID 33015170, 2020). "Demographic and laboratory features of patients with compensated cirrhosis due to virus C infection without HCC according to their AFP serum level." (PMID 32341704, 2020). "Multivariate analysis identified FIB-4 score ≥3.25 and AFP level >6 ng/ml after DAA treatment as independent factors that contributed to the development of HCC in patients without cirrhosis." (PMID 33284844, 2020). "Orthogonal partial least squares discriminant analysis was performed to discriminate the AFP-negative HCC from cirrhosis." (PMID 33014866, 2020). "Chi-square test indicated that CLU level was closely related to tumor stage (P = 0.006) and lymph node metastasis (P = 0.002), but not to gender, age, tumor size, serum AFP, vascular invasion, cirrhosis or recurrence (P > 0.05 for all)." (PMID 32039450, 2020). "In all of the patients, age, cirrhosis status, DM, albumin, AST, ALT, platelets, AFP 12M, APRI ≥ 0.90, APRI 12M ≥ 0.53, △APRI ≥ 0, FIB-4 ≥ 2.53, FIB-4 12M ≥ 2.56, and △FIB-4 ≥ 0 showed significant associations with HCC according to univariate Cox regression analysis." (PMID 32392752, 2020). "Another recent study by Ricco and colleagues investigated the time-related variability of AFP and PIVKA-II in serum samples of 418 patients with cirrhosis (124 HCC and 294 HCC-free controls) predominantly of viral etiology undergoing standard HCC surveillance by US." (PMID 33142893, 2020). "We cautiously draw a conclusion that elder age, male, elevated AFP, ALT, AST, and NLR, cirrhosis, HBeAg+, and no‐antiviral therapy were independent risk factors of HBV‐HCC." (PMID 32150664, 2020). "Compared with patients without HCC, the HCC group had significantly lower serum albumin and platelet count but higher serum total bilirubin, aspartate aminotransferase (AST), alanine aminotransferase (ALT), AFP level, the presence of HBV genotype C and cirrhosis." (PMID 32330203, 2020). "Numerous data have shown the nonspecific finding of significantly high serum AFP levels in patients with chronic liver disease and cirrhosis." (PMID 33490235, 2020). "This study reported that serum Sphingosine (d18:1)-1-P can potentially differentiate HCC, including AFP-negative HCC from cirrhosis." (PMID 33014866, 2020). "Among HBV‐HCC patients, AFP of antiviral group was 68% lower than no‐antiviral group in patients with cirrhosis (P = .005)." (PMID 32150664, 2020). "Univariate analysis of seven variables was conducted between tumour size < 5 cm and ≥ 5 cm; significant variables between the two groups included sex, age, race, AFP level, and no cirrhosis/cirrhosis." (PMID 32913474, 2020). "In the cirrhosis group, the AUC of AFP plus ALT, AST, and NLR was 0.873 (95% CI: 0.836‐0.903); with a sensitivity of 0.898 and a specificity of 0.769, better than any single use of AFP (P = .0052) or any indicator combination." (PMID 32150664, 2020). "Notably, AFP levels can be increased in patients with active hepatitis, and thus, AFP is less accurate in patients with active HCV infection, whereas AFP has higher sensitivity in other subgroups (e.g., patients with cirrhosis and HIV infection." (PMID 32944652, 2020). "The high risk of HCC development in patients with cirrhosis (i.e., 2–7% annual risk) justifies the recommendation of biannual HCC surveillance with abdominal ultrasound (US) with or without serum alpha-fetoprotein (AFP) in patients at high risk." (PMID 32741373, 2020).
Cirrhosis (continued). "However, critical circumstances like elevated levels of alpha-feto-protein (AFP), advanced cirrhosis, chronic HBV, NASH, and diabetes are on the top priority for screening." (PMID 32754608, 2020). "By employing multivariate Cox regression analysis (FIB-4 based model without the inclusion of the cirrhosis factor), DM, AFP 12M, FIB-4 12M ≥ 2.56, and △FIB-4 ≥ 0 were determined to be independent predictors of HCC." (PMID 32392752, 2020). "Univariate analysis of seven variables between M0 stage and M1 stage tumours identified that significant variables between the two groups included sex, age, ethnicity, marital status, AFP level, and no cirrhosis/cirrhosis." (PMID 32913474, 2020). "In the present study, we observed that serum values of AFP, PIVKA-II and GPC-3 were significantly different between patients with cirrhosis and those with HCC; however, the best accuracy for the detection of tumors was achieved by the combination of AFP + PIVKA-II." (PMID 33142893, 2020). "The result indicated that Sphingosine (d18:1)-1-P can also differentiate AFP-negative HCC from cirrhosis patients, and the R2Y (cum) and Q2 (cum) were 0.568 and 0.464, respectively." (PMID 33014866, 2020). "A retrospective study was conducted on a testing set—including 214 AFP‐NHCC patients, 200 cirrhosis, and 210 controls, and a validation set—including 140 AFP‐NHCC patients, 134 cirrhosis, and 128 controls recruited from The First Affiliated Hospital of Hunan Normal University." (PMID 31693242, 2020). "A total of 140 AFP‐NHCC, 134 cirrhosis, and 128 controls were recruited." (PMID 31693242, 2020). "It was observed that elderliness, male sex, cirrhosis, HBeAg+ or no‐antiviral therapy, and elevation of ALT, AST, neutrophil‐lymphocyte ratio (NLR), and AFP were associated with developing HBV‐HCC." (PMID 32150664, 2020). "Univariate analysis of seven variables between N0 stage and N1 stage tumours revealed that significant variables between the two groups included sex, race, marital status, AFP level, and no cirrhosis/cirrhosis." (PMID 32913474, 2020). "AFP, PIVKA-II and GPC-3 were measured in serum samples collected at tumor diagnosis in the 149 patients with HCC, and at the beginning of follow-up in the 200 patients with cirrhosis." (PMID 33142893, 2020). "The complete gene expression and clinical data (gender, age, and alanine aminotransferase (ALT)), cirrhosis, main tumor size, multinodular, BCLC stage, tumor node metastasis (TNM) stage, and α-fetoprotein (AFP) were contained among 185 patients in this dataset." (PMID 33163533, 2020). "Based on the univariate analysis, sex, platelet count, AFP level, APRI, FIB‐4 index, the presence of cirrhosis, and number of curative treatments for HCC before the DAA therapy were identified as factors that were significantly associated with HCC recurrence after the DAA therapy." (PMID 30900818, 2019). "The low expression of MFSD2A was significantly correlated with poor histological differentiation (P = 0.012), but not with age, sex, tumor size, live cirrhosis, lymph node metastasis, recurrence, serum AFP level, or HBsAg status." (PMID 31584009, 2019). "Sometimes the patient has no cirrhosis or hepatitis, and alpha-fetoprotein is not high, but imaging examination shows solid occupation and clear boundaries of the liver tumor, for which doctors should consider the primary liver nerve tumor." (PMID 31852101, 2019). "To evaluate whether the cirrhosis context was associated with the effect of risk factors on survival in long-term survivors, we conducted survival analysis for AFP and TBIL level in subset of cirrhosis." (PMID 30886700, 2019). "ROC analysis showed that the area under the ROC curve of AFP, DCP, AFP-L3%, VEGF, VEGFR2, ADAMTS13:AC, VWF:Ag, and the VWF:Ag/ADAMTS13:AC ratio for the early diagnosis of HCC in patients with cirrhosis was 0.61, 0.58, 0.54, 0.74, 0.67, 0.59, 0.67, 0.63, and 0.73, respectively." (PMID 31638892, 2019).
Cirrhosis (continued). "Variables that did not influence survival included age, gender, presence of cirrhosis, histological grade, tumor number, tumor size, surgical margin (< 1 cm vs. ≥ 1 cm), AFP level, and hepatitis status." (PMID 31291332, 2019). "The American Association for the Study of Liver Diseases (AASLD) recommends surveillance of patients with cirrhosis using ultrasound, with or without alpha-fetoprotein (AFP), every 6 months." (PMID 31275846, 2019). "Current AASLD guidelines recommend a one-size-fits-all screening strategy for HCC (abdominal ultrasound with or without serum AFP every six months) in patients with cirrhosis, regardless of etiology or the presence or absence of various risk factors." (PMID 30260995, 2018). "Some patients with cirrhosis and/or hepatic inflammation can have an elevated AFP, even without the presence of a tumor." (PMID 29717027, 2018). "Some patients with cirrhosis and/or hepatic inflammation can have an elevated AFP without the presence of tumor." (PMID 28077782, 2017). "Since there was an increase in the mean value of both S2-bound AGP, AFP and AGP when comparing HCC from cirrhosis patients, the performance of these markers were further analyzed using a combination of any two or all three markers using logistic regression analysis." (PMID 28296934, 2017). "Thus, a combination of AFP and S2-bound AGP gave an AUC of 0.83 in differentiating HCC from cirrhosis." (PMID 28296934, 2017). "Based on the current data, in the set of patients with cirrhosis, having the highest risk of HCC, the performance of APAR in differentiating HCC patients from cirrhosis patients is not better than AFP." (PMID 28827721, 2017). "It is well known that AFP levels increase in patients with active hepatitis or cirrhosis and without HCC, reflecting necroinflammation and regeneration; this fact is the major cause of its low specificity in high-risk population." (PMID 28620797, 2017). "A significant difference between different serum levels of miR-4651 among AFP (odds ratio [OR] = 11.72, 95% CI = 2.59-53.01), but not in age, gender, race, tumor sized, tumor grade, or cirrhosis was observed." (PMID 29113383, 2017). "Based on our present study, sAxl has an excellent diagnostic accuracy for the detection of advanced fibrosis/cirrhosis (AUC 0.918) and HCC at all stages (AUC 0.929) superior to AFP as well as has a favourable accuracy in HCC without cirrhosis (AUC 0.789)." (PMID 28526812, 2017). "Furthermore the assay discriminated significantly between cirrhosis and HCC samples with an AUC value of 0.77, which was similar to what was found when using AFP." (PMID 28296934, 2017). "In contrast, the baseline values of fasting plasma glucose, ALT, AFP and liver fibrosis or cirrhosis were lower in non-HCV subjects." (PMID 28107471, 2017). "The following variables: gender, age, AFP level, GGT level, tumor size, ALT level, HBV, HCV, cirrhosis, tumor encapsulation, number, invasion, distant metastasis, differentiation, TNM stage, BCLC stage, adjuvant TACE, microvascular density (MVD) and Ki-67 were chosen." (PMID 28099905, 2017). "Based on the ORs derived from each available study, we also evaluated the correlation between CD147 expression and some clinical characteristics, including tumor size, cirrhosis, differentiation, the TNM stage, lymph node metastasis, HBsAg, venous invasion, and serum AFP level." (PMID 28386553, 2017). "Moreover, cirrhosis HCC, which is more malignant and invasive, has high PKM2 levels were strongly correlated with AFP, multiplicity, TNM stage and tumour differentiation." (PMID 29127353, 2017). "Nomogram for cirrhosis involved PLT, age, AFP, GGT, HA, Albumin, and gender." (PMID 29235488, 2017). "Elevated AFP levels can also be due to non-HCC factors like chronic liver ailments such as cirrhosis and hepatic inflammation and other cancer types like non-seminomatous germ cell tumors and gastrointestinal cancers." (PMID 28031532, 2017).